CEACAM5 (CEA cell adhesion molecule 5)
Diseases named in the same sentence as CEACAM5 in open-access papers (continued):
Sharing a sentence is not in itself a finding about the gene and the disease.
tumor (continued). "In addition, MUC2 downregulation has been associated with increased expression of tumor-associated antigen carcinoembryonic antigen-related cell adhesion molecules 5 and 6 (CEACAM5 and CEACAM6), which are involved in cell adhesion, migration, tumor invasion, and metastasis." (PMID 29967641, 2018). "A more intricate situation was observed for the carcinoembryonic antigen [CEA, also termed carcinoembryonic antigen-related cell adhesion molecule 5 (CEACAM5)], which represents a classical soluble as well as membrane-expressed tumor marker in human clinical oncology." (PMID 25832000, 2015). "CEACAM1, CEACAM5 and CEACAM6 may be released from epithelial tumors in microvesicles, whereas tumor endothelia only contain CEACAM1 which has a receptor function for other CEACAMs, influences T cell behavior and regulates the tumor matrix and microvascularization." (PMID 25832000, 2015). "However, nearly no single anti-CEACAM5 mAb has been reported to have both tumor-targeting and tumor-suppressing activities." (PMID 21731662, 2011). "In addition, when comparing tumor tissues, patients who did not receive perioperative chemotherapy showed significantly higher CEACAM5 expression than those who received perioperative chemotherapy (p < 0.01), suggesting the potential of future personalized surgery." (PMID 40868067, 2025). "Since HL-60 and U937 do not express CEACAM-5 or CEACAM-6, it is very likely that NEO-201 binds to different types of cancers expressing core 1 and/or extended core 1 O-glycans attached not only to the tumor-associated variant of CEACAM5 and CEACAM6 but also to other protein carriers." (PMID 36991390, 2023). "In previous studies, we showed that NEO-201 specifically recognizes a tumor-associated variant of CEACAM5 and CEACAM6, which is not expressed in normal tissues, and proved that NEO-201 binds to both mammalian-expressed recombinant human CEACAM5 and CEACAM6 but not to CEACAM1 or CEACAM8 by ELISA." (PMID 36291783, 2022). "NILK-2401 induced phagocytosis of cancer cell lines expressing different CEACAM5 levels, but no clear correlation between EC50 and the CEACAM5-density on tumor cells was observed (R2 = 0.2244)." (PMID 38720892, 2024). "In contrast to the efficient killing of CEACAM5-positive tumor cells, NILK-2401 did not induce ADCC of the CEACAM5-negative cell line A549 or of primary epithelial cells, which further supports the selectivity of this BsAb to CEACAM5-positive tumor cells." (PMID 38720892, 2024). "Our anti-CEACAM5 CAR-T cells showed cytotoxicity in a CEACAM5 surface concentration dependent manner and reduced tumor growth in both ADC-responsive and -non-responsive CEACAM5-expressing NSCLC cells in vitro and in vivo." (PMID 36923424, 2023). "The high dose (10 mg/kg) of ADC SAR408701 analog suppressed A549 tumor growth (51% TGI) even in the absence of expressed CEACAM5, but anti-CEACAM5 CAR-T displayed no tumor growth inhibition." (PMID 36923424, 2023). "CEACAM5 and HMGB3 showed significant differences in expression between the two groups, and PLAU and ASS1 showed slightly higher expression in tumor tissues, but the difference was not statistically significant." (PMID 36397035, 2022). "Furthermore, CEACAM5 and AQP5 were significantly higher expressed in tumor-positive compared to tumor-negative lymph nodes and demonstrated particularly high T/N ratios, indicating their potential to detect metastatic lymph nodes for FGS and staging." (PMID 40379788, 2025). "The CD3 monovalent BsAb variant, which does not carry the CEACAM5-binding arm, did not induce relevant killing of the tested tumor cells (killing < 4%, eightfold less compared to NILK-2301, LS-174T), confirming that NILK-2301-mediated killing is CEACAM5-dependent." (PMID 38087365, 2023).
tumor (continued). "Noticeably, overexpressed NYESO1 (CTAGB1), MUC1, MAGEA3, MAGEA4, or CEA (CEACAM5) antigens did not correlate with TERT improved PFS of patients with high B cell infiltrate, suggesting a selective role of TERT over other common tumor antigens in driving local antitumor immunity." (PMID 36909826, 2023). "However, CEACAM5 and OPN are being colocalized in squamous carcinoma of tongue, and a significant correlation was observed between the positive colocalization and the negative colocalization in the depth of tumor invasion and the differentiation." (PMID 22738781, 2012). "Interestingly, CD44 kd tumors showed nearly abolished CEACAM5 immunoreactivity in the paranecrotic areas (again, the area where CD44 was expressed in control tumors) compared to control tumors (P < 0.0001, unpaired t‐test), but not at the tumor margin (P = 0.6)." (PMID 37849446, 2024).
cancer (734 papers, 1981 to 2026). A tumor composed of atypical neoplastic, often pleomorphic cells that invade other tissues. "Treatment with cibisatamab was found to enrich cancer cells with deficient CEACAM5 expression due to the activation of the WNT/β‐catenin pathway, which suppresses CEACAM5 expression." (PMID 40856433, 2025). "Among the two colorectal cancer patients who showed PRs, one had a KRASG12V mutation and both had 2+ membrane CEACAM5 expression in 100% of cancer cells." (PMID 39070179, 2024). "Differential gene expression analysis was performed, and GSEA identified EMT as the only cancer hallmark pathway that was significantly downregulated both in vitro and in vivo by CEACAM5 overproduction." (PMID 29736411, 2018). "The novel CEACAM5 variants in this study were probably cancer-specific transcripts that were processed by unpredictable alternative splicing." (PMID 24070190, 2013). "We identified two novel CEACAM5 splice variants in gastrointestinal (pancreatic, gastric, and colorectal) cancer cell lines." (PMID 24070190, 2013). "Additionally, a weak positive association with cancer marker CEACAM5 (rho = 0.1594, p < 0.0498) was observed." (PMID 36900088, 2023). "Furthermore, SPEM gastroids under the influence of conditioned media from metaplastic- or cancer-derived fibroblasts recapitulated dysplastic transition with an increase in the dysplasia marker CEACAM5 and a concomitant loss of the metaplasia marker AQP5." (PMID 37196797, 2023). "Furthermore, prostanoid and long-chain unsaturated fatty acid metabolic processes showed a significant association with cancer stemness and CEACAM5 expression." (PMID 36494785, 2022). "Comparison between patients categorized according to biomarker expression, using formula A, i.e. [KLK6/CEACAM5 + SLC35D3/CEACAM5 + POSTN/18S rRNA -MUC2/CEACAM5], with regard to risk for recurrence of disease and cancer death and observed recurrence 3 and 5 years after curative surgery." (PMID 32049988, 2020). "The anti-CEACAM5 VHH 6B11 is a good candidate for SPECT-based cancer diagnosis and can be potentially used as targeting moiety in the development of VHH-based drug conjugates for cancer treatments." (PMID 40358697, 2025). "CEACAM5, has been the focus of clinical trials for tusamitamab ravtansine, a drug designed for a spectrum of cancer types." (PMID 41049426, 2025). "Among the CEACAM family of proteins, CEACAM5 is a widely recognized biomarker and a validated candidate for targeted therapies across various cancer types." (PMID 40282889, 2025). "Anti-CEACAM5 VHH (6B11) affinity and specific cellular binding was confirmed by ELISA, FACS and immunofluorescence in cancer cell lines with varying CEACAM5 expression levels." (PMID 40358697, 2025). "Furthermore, the synergistic potential of multiple proteins (e.g., CDH17 and CEACAM5) may amplify risk through either additive or interactive mechanisms, which is consistent with the rationale for multi-target combination therapies in cancer." (PMID 41049426, 2025). "A comprehensive RNA-Seq analysis revealed significant mRNA upregulation of several genes, including ACTA1, IGFBP2, MUC5B, CEACAM5, and KRT19, all of which are associated with cancer progression in various types of malignancies (p < 10−10)." (PMID 40004774, 2025). "Another study shows that the cancer-associated Tn, T, and sialyl-Tn glycoforms of antigens such as MUC1 and CEACAM5." (PMID 40849468, 2025). "Meanwhile, panels of protein markers, mostly derived from epithelial tissues (CA-125, CEACAM5, etc.), have also been shown to be valuable for early cancer detection." (PMID 40117305, 2025). "CEACAM5 has been used as a marker for cancer diagnosis due to its overexpression in various cancers." (PMID 40358697, 2025). "Our findings demonstrate the utility of 99mTc-6B11 to non-invasively visualize CEACAM5-positive cancers using SPECT imaging and specific uptake has been confirmed ex vivo by γ-counting and autoradiography." (PMID 40358697, 2025).
cancer (continued). "Confocal microscopy visualization of 3D images enables the precise assessment of biomarker staining on the surface of cancer cells within the microenvironment, thus improving the effectiveness and efficiency of identifying promising biomarkers such as CEACAM5." (PMID 40868067, 2025). "Among the CEACAM proteins, CEACAM5 is a well-known biomarker and indicator of recurrence in cancer patients and an established candidate for targeted experimental anticancer immunotherapies, e.g., using antibody–drug conjugates or CAR T-cells." (PMID 38279989, 2024). "CEACAM5-positive cancer cells have been reported in liver metastasis patient samples, and colorectal cell lines producing high levels of serum CEACAM5 were highly metastatic to the liver in athymic mice." (PMID 38502695, 2024). "The results strongly support the further development of 2A3-CAR T-cells as a potential treatment strategy against CEACAM5/6-overexpressing cancers." (PMID 38279989, 2024). "While CEACAM5 shows limited expression in normal adult tissues, it is highly expressed in various cancers of the gastrointestinal tract, breast, pancreas, genitourinary system, and respiratory system." (PMID 39070179, 2024). "The concentration of CEACAM5 in the blood can predict cancer and monitor the treatment, progression, and prognosis of cancer." (PMID 38275310, 2024). "Gastroid cells strongly expressed CEACAM5 only after co-culture with either metaplasia- or cancer-derived fibroblasts, especially in the polypoid regions." (PMID 37196797, 2023). "Co-expression network showed genes closely associated with RAC1 were calculated among which cancer genes such as MUC1, MUC20, CEACAM5, andCCL20 were positively correlated to expression of RAC1 whereas TIMP3 and MGP was negatively correlated." (PMID 37202394, 2023). "Recently, the human carcinoembryonic antigen-related cell adhesion molecule 5 (CEACAM5, CEA, or CD66e) has been identified as target for cancer immunotherapy." (PMID 36923424, 2023). "Studies involving the CEACAM5 transgenic mouse focused mainly on developing therapies that targeted the CEACAM5 protein in cancer." (PMID 36741860, 2023). "We designed two novel TCEs by linking a scFv that recognizes CD3ε on either murine T cells (αCEA:mCD3) or human T cells (αCEA:hCD3) to a His-tagged scFv that binds human CEACAM5 on the surface of cancer cells." (PMID 36405739, 2022). "The reactivity of NEO-201 on colon, pancreas, lung normal and cancer tissues was compared to the reactivity of commercially available anti-CEACAM-5 and CEACAM-6 mAbs." (PMID 35804808, 2022). "CA125 (MUC16), CEA (CEACAM5), and HE4 (WFDC2) are clinically established diagnostic and prognostic markers of CESC; high levels of these biomarkers suggest cancer progression and poor prognosis." (PMID 34539641, 2021). "For all three individuals who were later diagnosed with stage 4 (metastatic) cancers, we observed carcinoembryonic antigen-related cell adhesion molecule 5 (CEACAM5) as an outlier in one or more pre-diagnosis samples." (PMID 33004987, 2020). "Although ten separate trajectories to cancer diagnoses were examined, CEACAM5 was observed to be a persistent outlier only in the three cancers each later diagnosed as metastatic, as well as one undiagnosed individual with skin lesions." (PMID 33004987, 2020). "The antigen recognized by NEO-201, a variant of CEACAM-5 and CEACAM-6, is specific to cancer tissue but expressed across cancer subtypes." (PMID 32637350, 2020). "Several bispecific formats for CEACAM5 targeting were reported for cancer immunotherapy over the years such as an anti CEACAM5/CD3 BITE (MEDI-565/AMG 211) or the head-to-tail 2:1 T cell bispecific antibody for treatment of CEA-positive solid tumors and others." (PMID 31447859, 2019). "CEACAM5 is a clinically well-established tumor antigen and is demonstrated to have a great concentration variation between cancer and controls." (PMID 31357969, 2019).
cancer (continued). "Carcinoembryonic antigen (CEA, also known as CEACAM5 or CD66e) was discovered in malignant tumors of endodermally derived epithelium of the gastrointestinal tract and pancreas." (PMID 28588612, 2017). "Our study would at evaluating the colocalization of OPN with CEACAM5 and the correlation with the carcinoma of tongue invasion and the degree of differentiation." (PMID 22738781, 2012). "Using immunohistochemistry, we found that normal tissue of tongue expressed CEACAM5 with apical and uniform membranous patterns, and the carcinomas mainly expressed CEACAM5 with a cytoplasmic pattern." (PMID 22738781, 2012). "CEACAM1, one of the binding partners of CEACAM5 in the CEACAM family, has been implicated in contact-dependent regulation of immune response associated with cancer." (PMID 21731662, 2011). "In many types of human cancers CEACAM5 is specifically expressed as a cell surface glycoprotein exhibiting several functions like regulating intercellular adhesion, differentiation and anoikis, cell polarization and tissue architecture." (PMID 21436956, 2011). "Using Col-1 monoclonal anti-CEACAM5 antibody we have previously developed a mimotope-based anti-CEACAM5 vaccine for the treatment of human carcinoma." (PMID 21436956, 2011). "Several genes that encode these proteins were upregulated in the CD26+ cancer cells: AGR2, BCMP11, CEACAM5/CD66e, CRISP3, KCNG3, KCNH8, LOX and NEO1." (PMID 20021671, 2009). "CEACAM5 is overexpressed in cancers of the gastrointestinal tract, pancreas, liver, gallbladder, lung, breast, female reproductive system, medullary thyroid, urinary bladder, and prostate." (PMID 17576469, 2007). "As CEACAM5 is highly expressed on the membrane of cells in a variety of epithelial cancers, it has been investigated as a radiolabeled biomarkers for future clinical cancer diagnosis." (PMID 40358697, 2025). "First, we investigated whether the developed naked anti-CEACAM5 VHHs 6B11 and 6F8 have anti-cancer activity." (PMID 40358697, 2025). "This study proved that the anti-CEACAM5 VHH 6B11 maintained good binding affinity and specificity after being labeled with 99mTc or Oregon Green 488, which has potential of being used as a diagnostic tool for CEACAM5 positive cancers." (PMID 40358697, 2025). "Besides, CEACAM5 was found to stimulate cancer progression by promoting cell proliferation and migration." (PMID 41233805, 2025). "Cancer divergence was present in this survey of CEACAM5 promoter methylation." (PMID 37942534, 2024). "We propose that a suitable drug delivery system, which targets CEACAM6 or CEACAM5 as markers of acid-resistant cancer cells, could be a promising molecularly stratified therapeutic strategy for CRC." (PMID 38502695, 2024). "When the original risk score was analyzed as a continuous outcome in the benign (low and high) subgroup as well as the “low and cancer” subgroup, the common proteins between the two subgroups, SFTPB and CEACAM5, were added to AKR1B10 to explain the variation of the risk scores." (PMID 37760474, 2023). "T-cell retargeting to eliminate CEACAM5-expressing cancer cells via CEACAM5xCD3 bispecific antibodies (BsAbs) showed limited clinical activity so far, mostly due to insufficient T-cell activation, dose-limiting toxicities, and formation of anti-drug antibodies (ADA)." (PMID 38087365, 2023). "Even though clinical translation of CEACAM5 targeting CAR-T cell therapies is still in preclinical stage, our CAR-T cell approach could provide a potential therapeutic strategy for CEACAM5-positive cancer patients with resistance to ADCs." (PMID 36923424, 2023). "CEACAM5 is a potentially useful biomarker in patients with certain cancers." (PMID 37645622, 2023). "Therapies targeting CEACAM5 in cancer are being developed to block this evading immune function." (PMID 36741860, 2023).